PLK3 (polo like kinase 3)
Diseases named in the same sentence as PLK3 in open-access papers (continued):
Sharing a sentence is not in itself a finding about the gene and the disease.
glioma (3 papers, 2022 to 2025). A benign or malignant brain and spinal cord tumor that arises from glial cells (astrocytes, oligodendrocytes, ependymal cells). "Collectively, our results suggest that PLK3 has the potential to become a diagnostic marker and therapeutic target for glioma." (PMID 39866232, 2025). "As an essential indicator of prognosis, gliomas with IDH wild-type status had considerably higher expression of PLK3 than gliomas with IDH mutations." (PMID 39866232, 2025). "In general, high expression of PLK3 was associated with a malignant process and poor prognosis in glioma patients." (PMID 39866232, 2025). "Accordingly, in glioma, the most relevant immune responses were positively associated with PLK3 expression." (PMID 39866232, 2025). "In our analysis of the immune function of PLK3 in gliomas, a positive association between PLK3 and T-cell immunity was found in regulatory T-cell differentiation and T-cell tolerance induction, both of which imply T-cell anergy and glioma aggressiveness." (PMID 39866232, 2025). "Thus, PLK3 expression was positively associated with the malignance and aggressiveness of glioma." (PMID 39866232, 2025). "Our previous analysis revealed a significant correlation between PLK3 expression and the neutrophil immune response in glioma." (PMID 39866232, 2025). "With the RNA-seq analysis of glioma, the expression of PLK3 increased with glioma grade, and it was highest for WHO grade IV glioma." (PMID 39866232, 2025). "In our selection of seven HRD-related genes, the high expression of PLK3, PRMT6, UNG, and FANCB is associated with poorer prognosis in glioma patients, whereas the high expression of POLR2F, INO80D, and PTEN is linked to better prognosis." (PMID 41417782, 2025). "To validate the functions of PLK3 in glioma, we genetically knocked down Plk3 in the GL261 cell line by lentiviral infection." (PMID 39866232, 2025). "Studies elucidating the immunoregulatory role of PLK3 in the glioma microenvironment and demonstrating that anti-PLK3 can prevent growth and promote immune-responsive gliomas are essential in the future." (PMID 39866232, 2025). "In terms of prognosis, the present study unveiled that high PLK3 expression indicated shorter overall survival in patients with different WHO grades of glioma and GBM." (PMID 39866232, 2025). "In both the CGGA dataset and TCGA dataset, PLK3 played a suppressive role in the anti-tumor immune response, and patients with high PLK3 expression in gliomas had a poor prognosis." (PMID 39866232, 2025). "For instance, genes like UNG and PLK3 play a significant role in most glioma cell lines, whereas PTEN and INO80D exhibit a weaker influence in the majority of cell lines." (PMID 41417782, 2025). "As far as we know, this is the first integrative study to explore the characteristics of PLK3 at both the clinical and molecular levels in whole-grade glioma." (PMID 39866232, 2025). "As there was a close association between PLK3 expression and T-cell immune response in glioma, the Gene Set Variation Analysis was performed to explore the connection between PLK3 expression and T-cell immunity in glioma." (PMID 39866232, 2025). "Both overexpression and knockdown of Plk3 were performed to investigate tumor cell growth in glioma, and the transplanted glioma mouse model demonstrated the role of Plk3 on tumor progression." (PMID 39866232, 2025). "We found that an increased level of PLK3 was associated with malignancy and poor prognosis of glioma, and further validated that PLK3 promoted glioma progression." (PMID 39866232, 2025). "Our analysis revealed a compelling correlation between elevated PLK3 expression and poor prognosis among patients with glioma." (PMID 39866232, 2025). "Determining the molecular characteristics of PLK3 may help to define it as a new target for glioma therapy." (PMID 39866232, 2025).
glioma (continued). "As desirable correlations between PLK3 expression and some immune checkpoints were obtained, immune treatment combined with PLK3 inhibitors may be a novel approach to glioma therapy." (PMID 39866232, 2025). "Finally, we confirmed that PLK3 expression can remodel the glioma microenvironment and suppress T-cell immune function." (PMID 39866232, 2025). "Through the analysis of transcriptomic and genomic profiling data, we found that PLK3 expression level was highly correlated to the malignancy of gliomas, and we validated that PLK3 could promote the GBM process in vitro and in vivo experiments." (PMID 39866232, 2025). "The survival assay showed a poor prognosis in PLK3 expression in WHO whole-grade gliomas." (PMID 39866232, 2025). "Our findings indicated that PLK3 expression level was highly correlated to the malignancy of gliomas, and we validated that PLK3 could promote the GBM progress in vitro and in vivo." (PMID 39866232, 2025). "We analyzed PLK3 expression in glioma samples from multiple databases." (PMID 39866232, 2025). "In this study, we found that increased expression of PLK3 was associated with more malignant glioma in terms of higher WHO grade through multiple analyses, IDH wild-type status, and the mesenchymal subtype of glioma samples." (PMID 39866232, 2025). "Our results confirmed that PLK3 can directly regulate glioma growth in vivo and in vitro." (PMID 39866232, 2025). "Accordingly, we consider that the function of PLK3 in the immune response in glioma is crucial." (PMID 39866232, 2025). "Given the intimate relationship with glioma malignance, PLK3 may play an important role in glioma progression." (PMID 39866232, 2025). "The results showed increased expression of PLK3 in samples from patients with glioma." (PMID 39866232, 2025). "However, the functions, molecular characteristics, and prognostic value of PLK3 in glioma remained unexplored." (PMID 39866232, 2025). "The results revealed a marked increase in PLK3 expression in glioma tissue." (PMID 39866232, 2025). "Therefore, the immunotherapy restraining activity of PLK3 may improve the prognosis of patients with glioma." (PMID 39866232, 2025). "However, studies reporting PLK3 expression and function in glioma are scarce." (PMID 39866232, 2025). "Clarifying the mechanism of PLK3 in gliomas may become a crucial step to cure this disease." (PMID 39866232, 2025). "Therefore, the role of PLK3 on neutrophils in glioma deserves further investigation." (PMID 39866232, 2025). "Furthermore, we demonstrated that PLK3 plays a key role in glioma development." (PMID 39866232, 2025). "Furthermore, it was predicted that PLK3 was synergistic with other checkpoint members in glioma." (PMID 39866232, 2025). "Furthermore, PLK3 played important roles in T-cell and neutrophil immune response in glioma." (PMID 39866232, 2025). "However, the impact of PLK3 in the glioma microenvironment remains largely elusive." (PMID 39866232, 2025). "The results showed that PLK3 expression was tightly correlated with TIM3 and B7H3 in whole-grade glioma, LGG, and GBM." (PMID 39866232, 2025). "The results showed connections between PLK3 and PD-1, and between PD-L1 and CD80, which revealed strong correlations among PD-1, PD-L1, and CD80 in whole-grade glioma, LGG, and GBM." (PMID 39866232, 2025). "However, the status of PLK3 in glioma still remains unclear." (PMID 39866232, 2025).
hepatocellular carcinoma (3 papers, 2016 to 2022). A malignant tumor that arises from hepatocytes. "In hepatocellular carcinoma, a weak mRNA and protein expression correlated with shorter patient survival due to promoter hypermethylation or loss of heterozygosity at the Plk3 loci." (PMID 27462786, 2016).
melanoma (3 papers, 2020 to 2024). A malignant, usually aggressive tumor composed of atypical, neoplastic melanocytes. "Recently, PLK3, another member of the PLK1 family, was reported to confer resistance to the MAPK pathway inhibitor in melanoma." (PMID 34718347, 2022).
anal carcinoma (2 papers, 2016 to 2019). "In conclusion, we here demonstrate that low expression of Plk3 and low levels of pT273 caspase-8 detection may, especially if combined with HPV-16 DNA-load, provide valuable prognostic markers in anal cancer." (PMID 27462786, 2016). "Consequently, as the prevalence of HPV-DNA in anal carcinoma commonly exceeds 90%, our data on the interrelationship between HPV16 DNA load/p16INK4a immunostaining and Plk3 or pT273 caspase-8 expression may provide additional informations to a histopathological assessment." (PMID 27462786, 2016).
anal squamous cell carcinoma (2 papers, 2016 to 2019). A squamous cell carcinoma (SCC) arising from the anal canal or the anal margin (perianal skin). "In the present study we aimed to investigate the clinical relevance of Plk3 expression and phosphorylation of caspase-8 at T273 in patients with anal squamous cell carcinoma (SSC) treated with 5-fluorouracil and mitomycin C-based chemoradiotherapy (CRT)." (PMID 27462786, 2016).
cervical carcinoma (2 papers, 2019 to 2021). A carcinoma arising from either the exocervical squamous epithelium or the endocervical glandular epithelium. "Here, we describe the association between disease-related outcomes and pre-treatment tumor PLK3 and pT273 Caspase 8 detection among locally-advanced cervical cancer patients." (PMID 31475104, 2019). "In summary, our data support the notion that increased pre-treatment tumor levels of PLK3 and pT273 caspase 8 predict for superior clinical response among cervical cancer patients treated with definitive CRT plus BT." (PMID 31475104, 2019). "In light of the hypothesized tumor suppressive role of PLK3 in cervical cancer, we advise caution in future clinical investigations regarding the utility of PLK1 inhibitors in this setting." (PMID 31475104, 2019). "In addition, low PLK3 expression was correlated with resistance to EBRT and BT, but not chemotherapy, in cervical cancer patients, again confirming the association of PLK3 levels with prognosis." (PMID 31475104, 2019). "The prognostic impact of PLK3 and its substrate pT273 Caspase 8, however, has not been evaluated in cervical cancer thus far to the best of our knowledge." (PMID 31475104, 2019).
head and neck cancer (2 papers, 2012 to 2022). A primary or metastatic malignant neoplasm affecting the head and neck. "PLK3 is often lowly expressed in lung, head and neck cancers." (PMID 35256538, 2022).
head and neck squamous cell carcinoma (2 papers, 2012 to 2016). A squamous cell carcinoma that arises from any of the following anatomic sites: lip and oral cavity, nasal cavity, paranasal sinuses, pharynx, larynx, and salivary glands. "Indeed, Plk3 has a tumor suppressor role in hepatocellular (HCC) and head and neck squamous cell carcinoma (HNSCC), while overexpression was correlated with shortened relapse-free survival time in breast and ovarian cancer." (PMID 27462786, 2016).
pancreatic cancer (2 papers, 2021 to 2024). "Here, in pancreatic cancer, the authors show that activation of Plk3 is dependent on its cleavage into p41Plk3, by the metalloendopeptidase nardilysin." (PMID 38605037, 2024).
acute myeloid leukemia (1 paper, 2024). Acute myeloid leukemia (AML) is a group of neoplasms arising from precursor cells committed to the myeloid cell-line differentiation. "As a low-molecular-weight, ATP-competitive kinase inhibitor, BI6727 effectively inhibits PLK1, PLK2, and PLK3 and has shown promising effects in various xenograft models and patients with acute myeloid leukemia (AML) (Gjertsen and Schöffski, 2015)." (PMID 39763588, 2024).
astrocytoma (1 paper, 2025). "Compared with other subtypes, such as astrocytoma, oligodendroglioma, and oligoastrocytoma, as well as their anaplastic variations, GBM was related to higher PLK3 expression." (PMID 39866232, 2025).
cystadenoma (1 paper, 2004). A benign or borderline cystic epithelial neoplasm arising from the glandular epithelium. "PLK 1 and PLK3 expression was low in normal ovarian surface epithelium and borderline tumours, with moderately higher expression levels in cystadenomas." (PMID 14970859, 2004).
Cystadenomas of the ovary (1 paper, 2004). "Cystadenomas of the ovary showed PLK3 positivity in five out of 17 cases (29.4%)." (PMID 14970859, 2004).
dry eye (1 paper, 2020). "During hyperosmotic stress-induced corneal epithelial cell death (an in vitro dry eye model), activation of Polo-like kinase 3 (Plk3) and c-Jun were observed to promote the cell death program." (PMID 33324655, 2020).
Follicular Cyst (1 paper, 2004). Cyst due to the occlusion of the duct of a follicle or small gland. "Theca externa of follicular cysts as well as corpora lutea expressed PLK3 strongly and homogeneously." (PMID 14970859, 2004).
liver cancer (1 paper, 2023). An epithelial or non-epithelial malignant neoplasm that arises from the liver. "PLK3, C9orf72, TRIM22, RNF152, FEZ1 and MEFV were dramatically downregulated in liver cancer patients, but upregulated by CTD treatment in HCC cells." (PMID 38017425, 2023).
lung adenocarcinoma (1 paper, 2021). A carcinoma that arises from the lung and is characterized by the presence of malignant glandular epithelial cells. "PLK2 expression was lower in lung adenocarcinoma (P < .05), and PLK3 was also under‐expressed in lung adenocarcinoma (P < .001)." (PMID 34080290, 2021). "Hou et al17 reported that PLK3 expression was decreased in lung adenocarcinoma (fold change = −2.348) and in lung squamous cell carcinoma (fold change = −1.890)." (PMID 34080290, 2021). "PLK3 was higher expressed in pneumocytes of lung tissue than that in either lung adenocarcinoma or lung squamous cell carcinoma." (PMID 34080290, 2021). "mRNA expression of PLK3 significantly increased in lung adenocarcinoma than that in normal sample, which was therefore likely that mRNA level of PLK3 would be a biomarker for male patient with lung adenocarcinoma." (PMID 34080290, 2021). "PLK3 was higher expressed in female than male only in lung adenocarcinoma." (PMID 34080290, 2021). "In lung adenocarcinoma, DNMT3A/3B had a negative correlation with PLK3." (PMID 34080290, 2021).
lung squamous cell carcinoma (1 paper, 2021). "PLK3 was found lower expressed in lung squamous cell carcinoma than normal sample." (PMID 34080290, 2021).
lymph node metastases (1 paper, 2024). "Furthermore, PLK3 has significantly higher expression in bone metastases than in lymph node metastases, whereas low PLK3 expression upon ALDH1A1 gain is found mainly in lymph node metastases but not in bone marrow metastases." (PMID 38169509, 2024).
osteoporosis (1 paper, 2015). A condition of reduced bone mass, with decreased cortical thickness and a decrease in the number and size of the trabeculae of cancellous bone (but normal chemical composition), resulting in increased fracture incidence. "Above all, our findings suggested a novel mechanism for osteoporosis, which is attenuation of monocyte apoptosis, as supported by the 4 apoptosis genes’ (DAXX, PLK3, VDAC1 and PDCD5) down-regulation in the low BMD subjects." (PMID 25659073, 2015).
osteosarcoma (1 paper, 2021). A usually aggressive malignant bone-forming mesenchymal neoplasm, predominantly affecting adolescents and young adults. "Lv et al38 reported that PLK3 suppressed the proliferation of osteosarcoma cell." (PMID 34080290, 2021).
pancreatic ductal adenocarcinoma (1 paper, 2025). An infiltrating adenocarcinoma that arises from the epithelial cells of the pancreas. "Mouse nardilysin cleaves glucagon and polo-like kinase 3 (Plk3) to generate an activated form of Plk3 that is important for the suppression of pancreatic ductal adenocarcinoma and contributes to the generation of cytotoxic T lymphocytes epitopes." (PMID 41463353, 2025).
Parkinson disease (1 paper, 2025). A progressive degenerative disorder of the central nervous system characterized by loss of dopamine producing neurons in the substantia nigra and the presence of Lewy bodies in the substantia nigra and locus coeruleus. "Beyond cancer, PLK2 and PLK3 have received attention in neurodegenerative diseases, because phosphorylation of synuclein at Ser129 is a hallmark of Parkinson disease and related synucleinopathies." (PMID 40379873, 2025).
scrapie (1 paper, 2020). A fatal disease of the nervous system in sheep and goats, characterized by pruritus, debility, and locomotor incoordination. "In addition, the brains of scrapie-affected hamsters show evidence of cell cycle activity with an increase in the proteins polo-like kinase (PLK) 1 and cyclin B1, and a decrease in PLK3 and Cdc25C." (PMID 32108870, 2020).
triple-negative breast carcinoma (1 paper, 2024). An invasive breast carcinoma which is negative for expression of estrogen receptor (ER), progesterone receptor (PR), and human epidermal growth factor receptor 2 (HER2). "Correlative expression of LINC00115, methylation PLK3, SETDB1, and HIF1α are prognostic for clinical triple-negative breast cancers." (PMID 38520019, 2024).